IL18 (interleukin 18)
Diseases named in the same sentence as IL18 in open-access papers (continued):
Sharing a sentence is not in itself a finding about the gene and the disease.
COVID-19 (continued). "Based on our comparison of the immunopathology underlying mycobacterial IRIS and COVID-19, we suggest that IL-18 may play a central role in this process and should be investigated further as a possible therapeutic target." (PMID 33841434, 2021). "The appropriate control of pro-inflammatory cytokines, including IL-18, may be a therapeutic option for managing the complications caused by the cytokine storm in COVID-19." (PMID 33732720, 2021). "Moreover, high levels of IL-18 were found to be associated with disease severity and poor clinical outcome in COVID-19 patients." (PMID 33823154, 2021). "Additionally, COVID-19 is linked to a proinflammatory shift in pregnant individuals, characterized by a reduction in Th2 cells and a lowered Treg/Th17 ratio, alongside an elevated Th1/Th2 ratio and IL-1β and IL-18 levels." (PMID 40497938, 2025). "Our data support the notion that the host’s genetic background can significantly affect COVID-19 clinical phenotype, also suggesting that the IL18-rs1834481, TLR2-rs5743708, and TLR4-rs4986791 polymorphisms may be used as molecular predictors of COVID-19 clinical phenotype." (PMID 37766191, 2023). "After adjustment for sex, age, and race, IL-18 levels were also significantly associated with risk of hospitalization day burden [P-value = 0.03, beta (β) = 5.68 days per natural log unit 1 increase in log (IL-18) levels] defined as total number of days hospitalized after COVID-19 diagnosis." (PMID 36894537, 2023). "This profile of a sustained, elevated IL-18 level associated with poor clinical outcomes is in keeping with our findings that persistently elevated fIL-18 levels from symptom day 15 onwards are significantly associated with disease severity and 60-day mortality, in COVID-19." (PMID 36823262, 2023). "Using the data presented here on IgM SARS-CoV-2 peptide reactivity and serum cytokine levels of IL-1α, IL-6, and IL-18, we have identified a unique biomarker panel which could be used for early identification of COVID-19 patients with increased risk of severe and potentially fatal disease." (PMID 35386707, 2022). "In conclusion, ferritin, D-dimer, CRP, NLR, cytokines (IL-6, IL-18, and IL-10), and cytokine receptors (IL-1Ra and sIL-2rα [sCD25]) in combination with clinical information may aid the early identification of patients at risk of critical COVID-19." (PMID 34422145, 2021). "Observational evidence concerning the role of interleukin-18 in reducing the risk of COVID-19 is limited and difficult to interpret because it concerns observational studies in patients where interleukin-18 could represent a protective response, a symptom or a cause of complications." (PMID 34911594, 2021). "The serum SP-D, CCL2/MCP-1, and IL-18 concentrations were significantly higher in the COVID-19 patients before admission to the hospital than those in the controls (p < 0.001 for all comparisons)." (PMID 42196173, 2026). "Serum from patients with severe COVID-19 induced increased levels of IL-1α, IL-1Ra, IL-5, IL-6, IL-10, IL-12(p40), IL-18, IL-27, and TNF-α." (PMID 41583455, 2025). "Instead, systemic IL-18 was the strongest indicator of myocardial edema/inflammation by cMRI after recovery from COVID-19." (PMID 39969260, 2025). "Here, we demonstrated that the unique signature featuring SLAMF1, CCL25, IL2-RB, IL10RA, IL15RA, IL18, and CST significantly increased the risk of critical illness in COVID-19 patients." (PMID 40475767, 2025). "RNAse1 and RNAse2 emerged as top regulators, as well as IL-18, a vital factor that influences various biological processes in COVID-19." (PMID 41226415, 2025). "A positive significant correlation between COVID-19 and 2 inflammatory proteins were suggested: IL-10 (OR = 1.18, 95% CI: 1.04–1.34, P = .01) and IL-18 (OR = 1.19, 95% CI: 1.04–1.36, P = .01)." (PMID 40101060, 2025).
COVID-19 (continued). "Cytokine levels are a crucial factor in the renal pathology of COVID-19 patients, compared to other viral infections, resulting in elevated levels of cytokines such as IL-1β, IL-6, IL-18, and TNF-α." (PMID 40863220, 2025). "In the present study, we found that human NALT contains a dense network of macrophages, including a FOLR2+ population, which expanded in convalescent COVID-19, expressing IL18, and pro-repair molecules, including type VI collagen." (PMID 39890933, 2025). "After adjustment for confounding factors, seven proteins that were highly abundant and associated with an increased hazard of critical COVID-19 outcome were SLAMF1, CCL25, IL2RB, IL10RA, IL15RA, IL18 and CST5." (PMID 40475767, 2025). "The MR results for IL-10, interleukin-10 (IL-18) and programmed death ligand-1 (PD-L1) with COVID-19 demonstrated P values of <.05 for IVW, and revealed consistent causal effects across the 5 methods employed." (PMID 40101060, 2025). "Admission IL-1β, and IL-33 were significantly lower, while IL-18 was significantly higher in cases when COVID-19 became more severe, along with significantly decreased FVIII, FXIII and plasminogen." (PMID 40303405, 2025). "We identified distinct cytokine expression patterns, with interferon-γ playing a key role in Post-COVID-19, and upregulated IL16 and IL18 expression serving as a hallmark of Post-Vaccination myocarditis." (PMID 39994453, 2025). "Some of these cytokines such as IL18 (asthma, COPD) and IL6 (COVID-19) are implicated in serious lung diseases." (PMID 41292845, 2025). "The elevated levels of IL-1β and IL-18 observed in COVID-19 patients with CRS support the involvement of the DDR and DNA sensing, via downstream inflammasome activation, amplifying inflammation and contributing to tissue injury." (PMID 40788382, 2025). "Pyroptosis was reported to regulate the release of proinflammatory cytokines, IL-1-beta and IL-18 in COVID-19 and bacterial sepsis." (PMID 40051620, 2025). "A recent study in solid-organ transplant recipients (SOTRs) with COVID-19 found a strong correlation between monocyte-derived cfDNA and pro-inflammatory cytokines, including IL-6 and IL-18." (PMID 40788382, 2025). "Single-cell transcriptome analysis of monocytes from patients with COVID-19 revealed a subset with high expression of Areg and IL-18 related to pyroptosis and enriched EGFR signaling pathway, specifically present in severe sepsis cases." (PMID 40292295, 2025). "We performed a 2-step MR analysis to examine the mediating pathways from IL-18 to COVID-19 by gamma-glutamylthreonine, and PD-L1 to COVID-19 by Betaine." (PMID 40101060, 2025). "The presence of increased plasma levels of sNLRP3, sCasp1p20 and IL-1 cytokines (IL-1β, IL-18) was demonstrated in hospitalized patients across the spectrum of COVID-19 severity." (PMID 39882243, 2024). "Elevated IL-18 and IFNγ levels were found in COVID-19 patients recently and their levels are known to be correlated to various lung diseases including ALI and acute respiratory distress syndrome (ARDS)." (PMID 38983847, 2024). "Six cytokines and chemokines, IL-10, IP-10, HGF, SCGF-β, IL-16, and IL-18, were identified for analysing the progression patterns of COVID-19, especially IP-10, which was closely correlated with SOFA scores." (PMID 38710800, 2024). "After analyzing 45 cytokines in the plasma of COVID-19 patients, we found that only the levels of IP-10, HGF, and IL-18 were significantly higher in COVID-19 patients compared to healthy and/or recovered subjects." (PMID 38486975, 2024). "Immunohistochemistry indicated higher levels of NLRP3 in post-mortem tissues from COVID-19 patients compared to controls, and there were correlations with Casp1p20 and IL-18 and disease severity [63•]." (PMID 38221578, 2024). "IL-6 and MCP-1 were found at higher levels in both groups, whereas MCP-1, IFN-g and IL-18, stood out among those with increased production in COVID-19 patients, compared to the vaccinated individuals." (PMID 39258622, 2024).
COVID-19 (continued). "The elevated levels of IL-18 and IL-1β were observed in patients with COVID-19, which were related to the severity of the disease." (PMID 38399989, 2024). "When stratifying according to disease severity, serum IL-18 was overall increased in all COVID-19 subgroups compared to controls." (PMID 39882243, 2024). "This warrants further investigation of the clinical potential of anti-IL-1R7 for treating patients with MAS, MAS-like clinical manifestations of COVID-19, and other IL-18-mediated inflammatory diseases." (PMID 38983847, 2024). "We and others have reported elevated levels of IL-18 in severe cases of COVID-19, with an emphasis on the levels of free IL-18 and IL-18BP." (PMID 39769266, 2024). "Statistically significantly higher levels of IL-18 were detected in the plasma of COVID-19 patients compared to recovered subjects (P < 0.05)." (PMID 38486975, 2024). "Furthermore, IL-18 is among the cytokines implicated in a cytokine storm that may be a sequalae of autoimmune and inflammatory diseases, viral infections, cancer, and severe cases of COVID-19." (PMID 39769266, 2024). "Another study reported that ICU patients with severe COVID-19 display higher levels of IL-18 than patients with moderate disease." (PMID 38710800, 2024). "We found significantly increased levels of interferon γ-induced protein 10 kDa, hepatocyte growth factor, and interleukin-18 in the plasma of COVID-19 patients." (PMID 38486975, 2024). "At the pandemic’s beginning, elevated cytokine levels (notably IL-6, GM-CSF, TNF, interferons, and IL-18) were commonly reported in severely ill patients with COVID-19, contributing to the cytokine storm." (PMID 39729489, 2024). "In particular, NLRP3 and NLRP1 inflammasome activation—as well as the components of its signaling, i.e., CASP1, IL-1β, and IL-18, etc.—show a relationship with the inflammatory factors and disease progression in patients with COVID-19." (PMID 38612539, 2024). "In the longitudinal analysis of patients’ disease development, we found that the levels of five cytokines and chemokines, IL-10, IP-10, SCGF-β, IL-16, and IL-18, significantly changed during the progression from mild to severe and from severe to mild COVID-19." (PMID 38710800, 2024). "Similar to LDGs from COVID-19 patients, HL-60 displayed comparable IL-18 secretion pattern upon LPS or IFN-I stimulation and nigericin-induced activation." (PMID 39172744, 2024). "The mediators MCP1, IFN-γ, and IL-18 stand out among those in which increased production was observed in COVID-19 patients." (PMID 39258622, 2024). "From day 0 to day 7, a significant induction of the inflammasome pathway genes, which included NLRC4, NLRP1, CASP1, PYCARD, and IL-18, was detected in COVID-19+ individuals compared to healthy controls." (PMID 38543837, 2024). "Sex differences in the immune response to COVID-19 have previously been described, where higher levels of proinflammatory markers such as IL-8, IL-18, and CCL5 were found in the serum of males with COVID-19 than in females." (PMID 39507250, 2024). "Clinically, COVID-19 patients had higher concentrations of Casp1p20 and IL-18 in their serum and NLRP3 activation in their peripheral blood mononuclear cells [63•]." (PMID 38221578, 2024). "We found that the brain, lung, and liver tissues from COVID-19 patients contained increased IL-1, IL-8, IL-12, IL-18, and TNF-α." (PMID 36609561, 2023). "IL-1RA and IL-18, which were both highly activated at 3 months after COVID-19, were significantly decreased and restored to normal means at 18 months after COVID-19." (PMID 36835948, 2023). "A total of 13/124 measures including CCL5, CCL17, IL-18, IFNα2, Fractalkine, classical monocytes, T cells, and CD4Temra exhibited significant sex differences in female vs. male COVID-19 patients." (PMID 37998327, 2023). "IL-8, IL-10, and IL-18 were increased in healthy pregnant women and remained elevated during COVID-19." (PMID 37036008, 2023).
COVID-19 (continued). "In contrast, IL1B and IL18 transcripts were expressed in the SPP1/MERTK+ (inflammatory monocyte-derived) macrophage cluster in the COVID-19-infected samples." (PMID 37737611, 2023). "Taken together, these data indicate that IL-1β, caspase-1, ASC and IL-18 are reliable biomarkers of COVID-19." (PMID 37168848, 2023). "Serum elevation of IL-18 can be regarded as a bad prognostic factor in COVID-19 in the Brazilian population." (PMID 36999046, 2023). "Studies have shown that the NLRP3 inflammasome is active and there are high levels of IL-1β and IL-18 in COVID-19 patients." (PMID 37631016, 2023). "The increase in systemic IL-1β and IL-18 levels is in accordance with other reports in critical COVID-19 patients." (PMID 37582864, 2023). "Elevated levels of IL-8, IL-10, and IL-18 were found in pregnant women in their healthy state, and these cytokine levels remained elevated during COVID-19." (PMID 37036008, 2023). "Some studies have reported an elevation in the proportion of monocyte forming specks, increased caspase-1 activity, and heightened production of IL-1β and IL-18 from peripheral blood mononuclear cells (PBMCs) in COVID-19 patients." (PMID 38140660, 2023). "Serum IL-18 levels in COVID-19 patients were noticeably higher compared to healthy controls, peaking in the group with severe pneumonia." (PMID 36926338, 2023). "Beyond lung damage, IL-18 also mediates the development of cardiovascular dysfunction, mimicking the spectrum of cardiac pathology observed in patients with COVID-19." (PMID 36894537, 2023). "Pyroptosis was found in COVID-19 patients with increases of IL-1β and IL-18, which further promoted the secretion of pro-inflammatory cytokines such as IL-6, IFN-γ, MCP-1/CCL2, MIP-1α/CCL3, MIP-1β/CCL4." (PMID 37631016, 2023). "Altogether, IL-18 is a promising cytokine that can prime hUC-MSCs to improve the efficacy of precision therapy against viral-induced pneumonia, such as COVID-19." (PMID 36707501, 2023). "The expression of inflammatory cytokines including IL-18 is actually upregulated in serum and plasma from severe COVID-19 patients." (PMID 36703213, 2023). "Inflammasome activation has been documented in COVID-19 patients with cardiac involvement, as shown by increased plasma levels of inflammasome markers including IL-1β, IL-1R antagonist (IL-1RA), IL-18 and IL-18-binding protein (IL-18BP)." (PMID 37251383, 2023). "SARS-CoV-2 maternal infections display higher frequencies of CXCR5+CD4+ and CCR6+CD4+ T cells and higher plasma concentrations of IL-6 and IL-18, when compared with gestational age–matched COVID-19–vaccinated counterparts." (PMID 37490342, 2023). "Lung samples from COVID-19 infected individuals demonstrate excessive neutrophil recruitment, infiltration, and activation, all established functions of IL-18.12–15 These observations support a critical role for IL-18 in COVID-19 lung injury." (PMID 36894537, 2023). "The concentrations of inflammasome-related markers, IL-1β, IL-18, gasdermin D, and lactate dehydrogenase, were significantly elevated in the serum and plasma of patients with COVID-19, compared with that of healthy donors." (PMID 36703213, 2023). "DEG analysis of IL1B/IL18+ COVID-19-infected BALF/lung versus IL1B/IL18+ control BALF/lung in the human, mouse, hamster, AGM, and ferret models showed host sDEGs and no viral sDEGs." (PMID 37737611, 2023). "IL-18 remains elevated longer than other cytokines in inflammatory and autoimmune disorders, including COVID-19." (PMID 36899824, 2023). "The most relevant cytokines that were significantly associated with mortality in COVID-19 patients were: IFN-β, IL-13, TNF-β, TGF-α, and IL-18/IGIF." (PMID 36851766, 2023). "Some elevated cytokine levels, such as interleukin-6 (IL-6), tumor necrosis factor (TNF), interferons (IFNs), granulocyte-macrophage colony-stimulating factor (GM-CSF), and interleukin-18 (IL-18), are often reported in severe-critical patients with COVID-19." (PMID 36679421, 2023).
COVID-19 (continued). "The levels of active caspase-1 and IL-18 were higher in the sera of COVID-19 patients than the controls." (PMID 37251383, 2023). "Increased IL-18 levels also exist in lung tissues of COVID-19 patients and SARS-CoV-2-infected mice." (PMID 36894537, 2023). "Amongst those with acute COVID-19, eleven markers significantly differed across disease severity categories: IL-1β, IL-2, IL-6, IL-10, IL-18, IL-23, IL-33, TNF-α, IP-10, G-CSF and YKL-40." (PMID 37063871, 2023). "Elevated proinflammatory cytokines such as IL-1β and IL-18 are characteristic of patients with severe COVID-19." (PMID 36703213, 2023). "Kaplan–Meier curves illustrate significant overall survival differences based on IL-18 levels starting from time of COVID-19 test to both 60-day follow-up (discharge or death) as well as to last follow-up." (PMID 36894537, 2023). "Differences in IL-8, IL-10, and IL-18 levels were evident during healthy pregnancy, and these cytokines remained elevated during acute and convalescent COVID-19." (PMID 37036008, 2023). "Our results show that the inflammasome signaling proteins IL-1β with an AUC of 0.91, and IL-18 with an AUC of 0.81 are the two most reliable biomarkers of the inflammatory response in COVID-19 among the inflammasome proteins analyzed in this study." (PMID 37168848, 2023). "Recent studies revealed heightened levels of inflammasome-associated products, IL-1β, IL-18, and LDH in COVID-19 patients, highlighting the inflammasome’s association with the disease." (PMID 37868953, 2023). "Cleaved caspase-1 and IL-18 were detected in the sera of COVID-19 patients and were positively correlated with disease severity, poor prognosis and other COVID-19 severity serum markers, including IL-6 and LDH." (PMID 36661317, 2023). "COVID-19 patients have increased levels of IL-18, which is involved in the generation of cytokine storms after SARS-CoV-2 infection." (PMID 36707501, 2023). "In summary, IL-18 is a potential novel biomarker of disease severity and outcomes in patients with COVID-19." (PMID 36894537, 2023). "Interleukin-18 (IL-18), a pro-inflammatory cytokine, was present at a high level among COVID-19 patients." (PMID 36999046, 2023). "Immune cell activation is reflected by high levels of IL-6, IL-1β, IL-18 known as the COVID-19 cytokine storm." (PMID 36776845, 2023). "Elevated levels of IL-8, IL-10, and IL-18 were found in pregnant women in their healthy state, and these cytokine levels remained elevated during acute and convalescent COVID-19." (PMID 37036008, 2023). "CD4Temra and T cell numbers were significantly higher, whereas IL-18 levels were significantly lower in female versus male COVID-19 patients." (PMID 37998327, 2023). "IL-18 is identified as one of 19 cytokines to stratify hospitalization and mortality in COVID-19 patients." (PMID 37998327, 2023). "Overall, the link between reduced mitophagy and inflammasome activation represents a novel mechanism during COVID-19 pathogenesis and suggests IL-18 and mitophagy as potential therapeutic targets." (PMID 36894537, 2023). "Taken together, these findings reveal a novel link between Spike signaling, mitophagy inhibition, and IL-18 activation, highlighting potential therapeutic targets for major COVID-19 cardiopulmonary complications." (PMID 36894537, 2023). "Mean plasma levels of IL-1β and IL-18, as products of inflammasome activity and pyroptosis, were higher in COVID-19 than in the other groups, as was the case for the alveolar cell damage marker sRAGE and GDF15 in the COVID-19 group." (PMID 37582864, 2023). "Based on a screening panel, IL-18 was identified amongst 19 cytokines to stratify mortality and hospitalization burden in patients hospitalized with COVID-19." (PMID 36894537, 2023). "It is worth noting that activation of the IL18/IL18R1/HIF-1 signaling axis was found to mediate an increased risk of peripheral vascular diseases such as aneurysms and atherosclerosis after COVID-19." (PMID 36851546, 2023).